HMGB1 (high mobility group box 1)
Diseases named in the same sentence as HMGB1 in open-access papers (continued):
Sharing a sentence is not in itself a finding about the gene and the disease.
epilepsy (continued). "In studies on animal models of epilepsy, HMGB1 has attracted attention." (PMID 36388178, 2022). "At the same time, a clinical study found that HMGB1 levels were proportional to the severity of epilepsy, and high levels of HMGB1 may represent an increased possibility of antiepileptic drug resistance." (PMID 36388178, 2022). "Anti-HMGB1 mAb may have the potential to downregulate P-glycoprotein expression which is overexpressed due to an increase in HMGB1 in epilepsy." (PMID 36310854, 2022). "Summary of studies on the HMGB1/TLR4 and IL-1β/ IL-1R pathways and their association with epilepsy." (PMID 35837232, 2022). "Anti-HMGB1 can help to regulate the occurrence of epilepsy and the process of epileptogenesis." (PMID 36310854, 2022). "Anti-HMGB1 only targeting HMGB1 (prevent translocation from nuclei) may be safer treatment to treat epilepsy." (PMID 36310854, 2022). "Animals with increased HMGB1 inflammatory subtypes in the blood before the onset may prospectively identify the possibility of epilepsy later." (PMID 35837232, 2022). "One of the current therapeutic strategies for epilepsy is to focus on molecular targeting of HMGB1 with specific antibodies or antagonists that have the potential to minimize the occurrence of epileptic seizures characterized by HMGB1 expression." (PMID 36310854, 2022). "HMGB1 is strictly involved in the inflammatory response related to epilepsy." (PMID 36310854, 2022). "Therefore, the HMGB1/TLR4 axis plays a key role in FCD-II-related epilepsy and mesial temporal lobe epilepsy." (PMID 35837232, 2022). "HMGB1 is used as a biomarker for neuroinflammation, epilepsy, and cognitive impairment." (PMID 35656438, 2022). "It is speculated that HMGB1 may be involved in the initiation of epilepsy after brain injury, and the level of HMGB1 in the blood might help to identify patients with a high risk of developing spontaneous seizures early after epileptogenic injury." (PMID 35837232, 2022). "There are currently limited data on HMGB1 inhibitors in animal models of epilepsy." (PMID 36388178, 2022). "Moreover, glial cell stimulation also triggers epilepsy, and this stimulation is mediated by HMGB1 through the TLR4/ NF-κB signaling pathway during seizures." (PMID 33921725, 2021). "Interestingly, higher circulating levels and increased expression of HMGB1 and TLR4 in epileptogenic tissue have been associated with increased risk and severity of epilepsy." (PMID 34198762, 2021). "The acetylated disulfide HMGB1 isoform was continuously expressed in patients with drug‐refractory epilepsy and could be used as a biomarker for human epilepsy occurrence and resistance." (PMID 33140586, 2021). "A potential biomarker for epilepsy known as high mobility group box-1 (HMGB1) has recently emerged." (PMID 34221552, 2021). "The pro-inflammatory signaling molecule HMGB1 has attracted particular attention as a possible mechanistic biomarker for epilepsy, with studies showing that, similar to the P2X7R, drugs interfering with HMGB1 signaling provide potent anticonvulsive and antiepileptic effects." (PMID 34572093, 2021). "HMGB1 being a pro-inflammatory like cytokine and its role in neuroinflammation has gained significant attention in epilepsy." (PMID 33732146, 2020). "Thus, it is of future interest to complete more detailed analysis applying techniques, which allow to study the ratio between HMGB1 isoforms in the brain tissue from dogs with epilepsy." (PMID 31959173, 2020). "Additionally, dogs with a seizure frequency of >3 times/month regardless of seizure etiologies presented insignificantly higher serum HMGB1 concentrations than did those with a seizure frequency of ≤3 times/month (epilepsy: P = .35, IE: P = .57, SE: P = .48)." (PMID 33150666, 2020). "Serum HMGB1 level is potentially involved in the induction and development of epilepsy or epileptic lesions and could be a potential predictive marker for epilepsy prognosis in humans." (PMID 33150666, 2020).
epilepsy (continued). "Receiver operating characteristic curve analyses in the present study supported the assertion that serum HMGB1 concentration could be a biomarker for canine epilepsy." (PMID 33150666, 2020). "However, we did not observe a compelling disease-modifying anti-epileptic effects of anti-HMGB1 mAb, as observed in a rodent model of epilepsy." (PMID 33732146, 2020). "Furthermore, it has been demonstrated that the elevation of serum HMGB1 concentration is related to epilepsy in human patients." (PMID 33150666, 2020). "Serum HMGB1 concentrations of all these dogs after the initiation of epilepsy treatment regardless of the cause of epilepsy were higher than those before the initiation of epilepsy treatment." (PMID 33150666, 2020). "Therefore, it was expected that there would be a change in serum HMGB1 concentration during epilepsy treatment according to the change in seizure frequency." (PMID 33150666, 2020). "Also, in epilepsy HMGB-1 is extensively discussed as an important mediator of neuroinflammation and as part of the pathophysiological mechanisms." (PMID 32581999, 2020). "Anti-HMGB1 mAb therapy or HMGB1-release inhibitors may provide an alternative approach to the control of epilepsy and epileptogenesis." (PMID 33321691, 2020). "The previous report about factors, including seizure type, disease course, seizure duration and frequency, associated with the elevation of serum HMGB1 level in human patients with epilepsy concluded that seizure duration and frequency were more related with serum HMGB1 concentration." (PMID 33150666, 2020). "In addition, serum HMGB1 concentrations of dogs with IE showing an epilepsy course of >3 months were also significantly higher than those of dogs with an epilepsy course of ≤3 months." (PMID 33150666, 2020). "In this review, we will focus on the breakdown and disruption of the BBB under different conditions, including brain infarction, brain hemorrhage, brain trauma, epilepsy, degenerative diseases, and systemic inflammation, and we will discuss the involvement of released HMGB1 in the processes." (PMID 33321691, 2020). "In this context, it is of particular interest that a recent study confirmed that the pathologic disulfide HMGB1 isoform might serve as a mechanistic biomarker for epilepsy development and early epilepsy manifestation in rodent models and patients." (PMID 31959173, 2020). "Although pharmacologic inhibition of HMGB1 has been successful in experimental models of epilepsy." (PMID 31156384, 2019). "Interestingly, anti-HMGB1 mAbs had a long-term anti-seizure effect with minimal side effects in a mouse epilepsy model." (PMID 30891101, 2019). "Therefore, we conducted this case-control study to investigate the association of serum HMGB1 and TLR4 expressions with the risk of epilepsy as well as their correlations with disease severity and anti-epilepsy drugs resistance." (PMID 31241711, 2019). "High mobility group box-1 (HMGB1) has recently emerged as a potential biomarker of epilepsy." (PMID 31312171, 2019). "In epilepsy studies, HMGB-1 has gathered increasing attention because it has been hypothesized that it may play a role in epileptogenesis, being both a pharmacological target and a biomarker for the silent phase of the disease." (PMID 31507379, 2019). "For example, miRNA-129-5p negatively regulates HMGB1 during epilepsy." (PMID 31312171, 2019). "For instance, HMGB1 is responsible for the unfavorable inflammatory effects in epilepsy." (PMID 31241711, 2019). "Glial cells activation has been reported to serve an important role in the development of epilepsy and HMGB1 may mediate microglial activation via the TLR4/NF-κB signaling pathway during seizures." (PMID 30271319, 2018). "The focus of the topic is TBI, neuroinflammation, epilepsy and cognitive decline, however, blocking HMGB1 might achieves significant neuroprotection in several forms of neurodegenerative disorders where neuroinflammation plays a crucial role." (PMID 30271319, 2018).
epilepsy (continued). "Extensive work has cast light on the role of high-mobility group box 1 (HMGB1), an inflammatory mediator, in the pathogenesis of various neurological diseases, including Alzheimer’s disease, Huntington’s disease, Parkinson’s disease, and epilepsy." (PMID 30013568, 2018). "Targeting HMGB1/TLR4/RAGE signaling for epilepsy has gained more attention in recent years." (PMID 30271319, 2018). "Recently, HMGB1 has received greater attention for its role in epilepsy." (PMID 30271319, 2018). "Interestingly, accumulating evidence suggests that neuroinflammation is highly associated with epilepsy and cognitive dysfunction after TBI and HMGB1 exhibits a key role as an initiator and amplifier of neuroinflammation as well as in neuronal excitation." (PMID 30271319, 2018). "Overall findings suggest that blocking the HMGB1/TLR4/RAGE regulatory axis may represent a novel method for treating epilepsy." (PMID 30271319, 2018). "Anti-HMGB1 monoclonal antibodies (mAbs) have demonstrated beneficial effects on epilepsy and TBI." (PMID 30271319, 2018). "This study was designed to determine whether HMGB1 is involved in the pathogenesis of epilepsy or the ability of anti-HMGB1 mAb to protect BBB permeability, neurons and inflammation." (PMID 28446773, 2017). "Furthermore, HMGB1 has been demonstrated as an excitatory and neurotoxic signaling molecule in the CNS and exerts a prominent role in conditions like epilepsy." (PMID 27822212, 2016). "In addition, whereas HMGB1 translocation in adult models of epilepsy has typically been reported in astrocytes and microglia, in the eFSE model we find the translocation exclusively in neurons during the first few hours." (PMID 26730400, 2015). "Levels of HMGB1 are increased in children with febrile seizures, and increased expression of HMGB1 contributes to the generation and perpetuation of seizures in humans or mouse models of epilepsy." (PMID 26518260, 2015). "Knowledge about the expression of HMGB1 in epilepsy is still highly limited." (PMID 26485677, 2015). "Such evidence indicated that HMGB1 could be a biomarker of epilepsy." (PMID 41155637, 2025). "Moreover, experimental epilepsy models demonstrated that blockade of either HMGB1 or genetic deletion of TLR4 using neutralizing antibodies significantly reduced seizure incidence, thereby validating the pathogenic role of the HMGB1/TLR4 pathway in epilepsy." (PMID 41306289, 2025). "Moreover, concentrations of HMGB1 could be predictors of drug treatment response in patients with epilepsy." (PMID 41155637, 2025). "Recent research studies show that the translocation of HMGB1 in the thalamic reticular nucleus is promoted by kainic acid and inhibited by perampanel, suggesting that anti‐inflammatory treatment may become an important measure for epilepsy treatment." (PMID 40103702, 2025). "Moreover, HMGB1 is released by immune cells or glia cells and neurons in the CNS, and release is upregulated in the brain of epileptic patients and epileptic animal models, strongly implicating this protein in the pathophysiology of epilepsy." (PMID 38332381, 2024). "TLR4 agonists, LPS and MPL, can attenuate seizure severity in pilocarpine-induced rats with temporal lobe epilepsy, and pentoxifylline may represent a promising drug to inhibit epilepsy progression by targeting the HMGB1/TLR4/RAGE signaling pathway in pentylenetetrazol (PTZ)-kindling rats." (PMID 35837232, 2022). "This molecule could be targeted by specific therapies, since monoclonal antibodies against HMGB1 demonstrated to be effective in refractory epilepsy and glycyrrhizin, an additional HMGB1 inhibitor, was able to protect from neuronal inflammation in a mouse model of autoimmune encephalomyelitis." (PMID 35558368, 2022). "In addition, micro-RNA plays a role in HMGB1-mediated epilepsy." (PMID 35837232, 2022). "Therefore, inhibition of the overexpression of P-glycoprotein via anti-HMGB1 mAb may be able to become a therapeutic target for epilepsy." (PMID 36310854, 2022).
epilepsy (continued). "Furthermore, this finding reflects that HMGB1 might reflect as an emerging extracellular target against epilepsy." (PMID 33732146, 2020). "Our finding reporting increased mRNA expression of HMGB1 in an epileptic group (repeated dose pilocarpine) is in similar line with earlier studies supporting the notion that HMGB1 might play a crucial role in the pathogenesis of epilepsy." (PMID 32260203, 2020). "Therefore, the difference in the routinely prescribed antiepileptic drugs might have led to the differences in the effects of antiepileptic drugs on the serum HMGB1 concentrations in dogs and humans with epilepsy." (PMID 33150666, 2020). "Therefore, this study aimed to elucidate the factors that could affect serum HMGB1 levels including etiology, status, and treatment of epilepsy." (PMID 33150666, 2020). "Therefore, unlike the previous report about the relationship between human epilepsy and serum HMGB1 concentration, serum HMGB1 concentration and seizure frequency may not be related in dogs with epilepsy." (PMID 33150666, 2020). "Thus, pharmacological targeting of HMGB1 might also be of interest for management and prevention of canine epilepsy." (PMID 31959173, 2020). "In order to determine whether active inflammation, including high mobility group box-1 (HMGB1) and pro-inflammatory cytokines, occurs in children with febrile seizures or epilepsy, we analyzed cytokine profiles of patients with febrile seizures or epilepsy." (PMID 21989210, 2011). "In summary, the HMGB1/TLR4 pathway and IL-1/IL-1R1/IL-1Ra pathway partly share similar mechanisms in neuroinflammation of epilepsy." (PMID 41155637, 2025). "However, the exact mechanisms by which the HMGB1/TLR4 axis contributes to epilepsy remain unclear." (PMID 40894200, 2025). "In this review, we mainly focus on the IL-1β/IL-1R1/IL-1Ra pathway and HMGB1/TLR4 pathway, in which recent advances in knowledge have been made for epilepsy." (PMID 41155637, 2025). "A previous study involving 145 poststroke epilepsy patients compared a LTG plus VPA treatment group and a VPA-only group in terms of the serum HMGB-1, matrix metalloproteinase (MMP)-9, and IL-6 levels." (PMID 40806813, 2025). "Towards clinical translation, we carefully reviewed existing substances and drugs targeting the IL-1β/IL-1R1/IL-1Ra pathway and HMGB1/TLR4 pathway and their effects on epilepsy models and patients." (PMID 41155637, 2025). "Gene expression levels of the HMGB1/RAGE/TLR4/NF‐κB signalling pathway, which is effective in both epilepsy and toxoplasmosis, were determined in patients with idiopathic epilepsy." (PMID 39046369, 2024). "Specifically, flavones primarily counter epilepsy through interactions with pathways such as NF-κB p65, the TLR4/MyD88/NF-κB axis, PPAR-γ, MAPK, HMGB1, IGF1R, NLRP3, and MAO-B, which are essential in mitigating neuroinflammation." (PMID 39329119, 2024). "Among these, the HMGB1/RAGE/TLR4/NF‐κB signalling pathway has been shown by clinical and preclinical studies to play a significant role in epilepsy, in addition to its role in many neurological diseases." (PMID 39046369, 2024). "Liquid biomarkers have also been investigated; for example, serum High-mobility group box 1 (HMGB1) and interleukin (IL)-1β have been related to epilepsy outcomes in the pediatric population, and neuron-specific enolase has been used to predict the outcome." (PMID 39337003, 2024). "HMGB1 and the PRR it can signal through, TLR4, have increased expression in human and animal epilepsies." (PMID 36035987, 2022). "Here, HMGB1/TLR4 and IL-1β/IL-1R inflammasomes in the pathogenesis of epilepsy are reviewed and future perspectives are outlined." (PMID 35837232, 2022). "HMGB1/TLR4/IL-1β/IL-1R pathway, HMGB1/TNF-α/TRADD pathway, and TRAF-2 are the key initiators of neuroinflammation for epilepsy and cognitive impairments." (PMID 35656438, 2022).
epilepsy (continued). "For instance, high-mobility group box 1 (HMGB1), a key mediator of neuroinflammation with increased levels in patients with epilepsy, is significantly increased in the blood serum of epileptic dogs." (PMID 35812852, 2022). "Therapies interfering with HMGB1/TLR4, NF-κB, IL-1β, COX-2, PGE2/EP2, and TGF-β signaling pathways, and other inflammatory targets have been proposed to treat epilepsy." (PMID 34830412, 2021). "Similar pathways, mediated via HMGB1, RAGE, and TLR4 were shown to be upregulated in epilepsy animal models and surgical resections of epilepsy patients." (PMID 34966269, 2021). "Thus, serum HMGB1 concentration could be a useful screening tool for detecting canine epilepsy." (PMID 33150666, 2020). "The release of HMGB1 from glial cells and neurons reduces seizure threshold via HMGB1‐mediated IL‐1β and neuronal toll‐like receptor (TLR) 4 activation in rodent models of epilepsy." (PMID 33150666, 2020). "Overexpression of extracellular HMGB1 was observed in several neuroinflammatory conditions, including TBI, Subarachnoid hemorrhage (SAH), Epilepsy, Alzheimer’s diseases (AD), Amyotrophic lateral sclerosis (ALS) Parkinson’s diseases (PD), etc." (PMID 32610502, 2020). "Therefore, although it was not possible to be certain whether the increased serum HMGB1 level in the dogs was the cause or result of seizure, it could indicate the presence of epilepsy." (PMID 33150666, 2020). "This statement is attributed to the fact that there was an increased level of HMGB1 and TLR4 in both experimental epilepsy and epileptic brain samples from the human." (PMID 33732146, 2020). "These animal experiments and clinical studies suggested that both HMGB1 and TLR4 expressions are upregulated in epilepsy cases." (PMID 31241711, 2019). "HMGB1/TLR4 or/TLR2 axes contribute to regulate inflammation during lung and liver injury, epilepsy, cancer, and heart disease." (PMID 30306212, 2019). "Expressions of both HMGB1 (6.3, 4.4−7.8 ng/mL vs 1.9, 2.4−3.3 ng/mL, P<0.001) and TLR4 (3.0, 2.3−3.6 ng/mL vs 0.9, 1.3−1.7 ng/mL, P<0.001) in epilepsy patients were greatly elevated compared with HCs." (PMID 31241711, 2019). "In recent days, research using experimental and clinical models has focused on the pathogenesis of how HMGB1 proteins contributes to TBI, neuroinflammation, epilepsy and cognitive decline." (PMID 30271319, 2018). "- The nuclear protein HMGB1 is a mediator for neurological conditions such as TBI, neuroinflammation, epilepsy and cognitive dysfunction." (PMID 30271319, 2018). "A recent study found that TLR4 activation by high-mobility group box-1 (HMGB-1, a well-known TLR4 endogenous ligand) is involved is seizures, while another study found that neuronal KC is significantly increased during epilepsy in the rat." (PMID 23034047, 2012). "HMGB1 is highly expressed in human epileptogenic brain, and antagonists of HMGB1 and TLR4 have been demonstrated to retard seizure precipitation and to decrease acute and chronic seizure recurrence in epilepsy animals." (PMID 21989210, 2011). "A case-control study investigating the correlation between NLRP3 expression and HMGB1 levels in the serum of children with febrile epilepsy revealed that serum levels of HMGB1, NLRP3, caspase-1, IL-1β, IL-6, and TNF-α were significantly higher in children with epilepsy compared to controls." (PMID 40688353, 2025). "Although no drugs targeting the HMGB1/TLR4 pathway for epilepsy are currently in clinical trials, many substances can target this pathway and thus exhibit anti-epileptic effects." (PMID 41155637, 2025). "HMGB1 antagonists and TLR4/RAGE inhibitors are two preclinical approaches to blocking this system that have demonstrated therapeutic benefits in models of traumatic brain injury, neuroinflammation, epilepsy, and cognitive decline." (PMID 40941042, 2025).